NBAT1 (neuroblastoma associated transcript 1)
Synonyms: NBAT-1; formerly CASC14
Gene: Long non-coding RNA gene on chromosome 6 (22,133,205 to 22,222,641, reverse strand). Ensembl gene ENSG00000260455.
Diseases named in the same sentence as NBAT1 in open-access papers:
NBAT1 is named in the same sentence as 30 diseases in open-access papers, as found by Europe PMC text mining. Sharing a sentence is not in itself a finding about the gene and the disease. The quoted sentences say what the papers report.
neuroblastoma (25 papers, 2015 to 2024). Neuroblastoma (NB) is the most common solid, extracranial childhood tumor. "We know, for example, that the hypermethylation of the promoter of NBAT1 leads to low NBAT1 expression in high-risk neuroblastoma, but the mechanisms underlying the disrupted expression of most other lncRNAs are not well understood." (PMID 38891878, 2024). "The difference in NBAT1 expression between low- and high-risk neuroblastoma has been attributed to CpG methylation of its promoter and the presence of certain functional polymorphisms on chromosome 6p22." (PMID 38891878, 2024). "It was found that the loss of lncRNA neuroblastoma-associated transcript-1 (NBAT-1) contributed to aggressive neuroblastoma by activating REST." (PMID 37892159, 2023). "The loss of NBAT-1 inhibits neural differentiation, promotes neuroblastoma tumor development, and correlates with poor survival rates in neuroblastoma patients." (PMID 37345170, 2023). "For example, neuroblastoma associated transcript 1 (NBAT1) is demonstrated as a tumor-suppressing LncRNA and habitually downregulated in several cancers including neuroblastoma, osteosarcoma, ovarian cancer, and breast cancer." (PMID 34759954, 2021). "The CASC15 lncRNA is transcribed in an antisense manner with another non-coding gene NBAT1, which is also associated with neuroblastoma progression." (PMID 31920530, 2019). "One such example is the lncRNA neuroblastoma-associated transcript 1 (NBAT-1) which was associated with good prognosis in high-risk neuroblastoma patients." (PMID 31781490, 2019). "The lncRNA “Neuroblastoma associated transcript 1” (NBAT1) is located on chromosome 6 and is known to control neuroblastoma progression by regulating cell proliferation and neuronal differentiation." (PMID 27092491, 2016). "Based on these observations, we proposed that a higher level of NBAT1 in low-risk tumors controls neuroblastoma progression and promotes neural differentiation." (PMID 25859549, 2015). "Loss of NBAT1 contributes to the aggressiveness of neuroblastoma by promoting proliferation and by impairment of differentiation of neuronal precursors." (PMID 26378045, 2015). "Our study demonstrated that the lower levels of NBAT1 in high-risk patients are due to two intricate transcriptional regulatory mechanisms involving CpG methylation and genotype at the high-risk neuroblastoma-associated SNP rs6939340." (PMID 25859549, 2015). "NBAT-1 (a lncRNA neuroblastoma-associated transcript-1), which maps to the 6p22 locus, was first identified by Gaurav Kumar Pandey as a biomarker to predict the clinical results of neuroblastoma." (PMID 38243168, 2024). "Indeed, a recent sequencing transcriptomes analysis of low- and HR neuroblastomas pinpointed a lncRNA neuroblastoma associated transcript-1 (NBAT-1) as a biomarker that predicted neuroblastoma patients outcome." (PMID 28178969, 2017). "On the contrary, the hypermethylated NBAT1 promoter and the G/G genotype at the disease associated SNP in high-risk neuroblastomas results in decreased expression of NBAT1, leading to highly proliferative and invasive neuroblastoma cells with an impaired ability to differentiation." (PMID 25859549, 2015). "Decreased expression of NBAT1 is associated with poor clinical outcome in neuroblastomas." (PMID 26378045, 2015). "Loss of neuroblastoma-associated transcript-1 (NBAT-1) contributes to aggressive NB by increasing cellular proliferation, invasion and impairing differentiation of neuronal precursors." (PMID 31787850, 2019). "Cancer susceptibility 15 (CASC15) and neuroblastoma associated transcript 1 (NBAT1) are tumor suppressors that are located at the NB risk-associated 6p22.3 locus." (PMID 31480503, 2019). "For instance, the expression of lncRNA, neuroblastoma associated transcript-1 (NBAT-1) is down-regulated in high-risk NB and associated with poor patient survival." (PMID 27517149, 2016).
neuroblastoma (continued). "In neuroblastoma, NBAT-1 affects target genes relevant to cell invasion and proliferation in epigenetics by acting as a scaffold for EZH2, and by mechanically inhibiting the NRSF/REST pathway the neural differentiation is controlled by it as well." (PMID 38243168, 2024). "Mechanistically, NBAT-1 down-regulation enhances proliferation and invasion of neuroblastoma cells through suppression of expression of target genes as well as induction of expression of neuronal-specific transcription factor NRSF/REST." (PMID 33718173, 2021). "Suppression of NBAT‐1 by knockdown in the SH‐SY5Y human neuroblastoma cell line results in increased cancer cell viability and invasiveness, whereas overexpression leads to decreased cell proliferation and invasion." (PMID 32100288, 2020). "Similar to other transcriptomic analyses in cancer, the presence of the T-UC.3004, linc00467, NBAT1, and Pauppar lncRNAs has been reported during the pathogenesis of neuroblastoma." (PMID 31920530, 2019). "Considering that NBAT-1 is expressed at low levels in high-risk neuroblastoma, NBAT-1 acts as a scaffold for EZH2 recruitment and represses NBAT-1/EZH2 target genes, which are involved in neuroblastoma progression." (PMID 29458374, 2018). "Functional characterization of NBAT1 as a novel biomarker for neuroblastoma revealed its property as a tumor suppressor, making it a highly attractive target for novel therapeutic strategies for high-risk neuroblastoma patients." (PMID 25859549, 2015). "NBAT1 expression is upregulated during retinoic acid induced neuronal differentiation of neuroblastoma cells." (PMID 25859549, 2015). "In addition, in neuroblastoma, NBAT-1/CASC15/MYCN/USP36/COL18A1 controls a new oncogenic pathway, as revealed by Prasanna Kumar Juvvuna." (PMID 38243168, 2024). "Thus, SOX9 appears to be one of the key genes in neuroblastoma progression, whose oncogenic functions are controlled by NBAT1 and CASC15-003." (PMID 36230680, 2022). "Taken together, these findings suggest that NBAT‐1 is a ‘protector’ against neuroblastoma." (PMID 32100288, 2020). "The authors showed that NBAT-1 was necessary for differentiation of neuronal precursors and that hypermethylation of its promoter region and following gene down-regulation increases neuroblastoma cells proliferation." (PMID 28178969, 2017). "Although it was previously reported that low expression of NBAT1 was significantly correlated with poor overall and event free survival of neuroblastoma patients, the expression of NBAT1 in other cancer was still unknown." (PMID 26378045, 2015). "For example, lncRNAs such as HOTAIR (breast cancer), NKILA (breast cancer metastasis), NBAT1 (neuroblastoma), MALAT1 (lung, breast, prostate and cervix cancer), MDC1-AS (bladder cancer), lncRNA-886 (esophageal and gastric cancers) and PCAT-1 (prostate cancer) have been implicated in tumorigenesis." (PMID 26087192, 2015). "NBAT1 is identified in neuroblastoma as a tumor-suppressing lncRNA." (PMID 26378045, 2015). "Moreover, NBAT1 expression can be used as an independent prognostic marker for prediction of event-free survival in neuroblastoma patients." (PMID 25859549, 2015). "Our observations on NBAT1 open up novel lncRNA based treatment approaches for neuroblastomas." (PMID 25859549, 2015). "LncRNA NBAT1 (also called CASC14), the expression of which is decreased in neuroblastoma, functionally interacts with PRC2 member EZH2 and controls the expression of target genes via the loss of H3K27me3 from their promoter regions, resulting in neuroblastoma development." (PMID 32366932, 2020). "These lncRNAs include CASC15 (alias LINC00340) and NBAT1 (alias CASC14), and their role in neuroblastoma carcinogenesis has been further elucidated." (PMID 31920530, 2019).
neuroblastoma (continued). "Being described as tumour suppressor, NBAT-1 might be among crucial regulatory RNAs and so, the therapy against NBAT-1 and its downstream effectors could be a potential novel therapeutic option for the treatment of HR neuroblastoma." (PMID 28178969, 2017).
breast carcinoma (8 papers, 2015 to 2025). "In particular, reduced NBAT1 in breast cancer is associated with tumor metastasis and poor clinical outcome." (PMID 29443889, 2018). "In breast cancer, low NBAT-1 expression levels are associated with poor survival, as well as the development of lymph node metastases." (PMID 27608009, 2016). "Especially, NBAT1 reduction was associated with poor patient survival as well as with lymph node metastases in breast cancer." (PMID 26378045, 2015). "Particularly, reduced NBAT1 in breast cancer is associated with tumor metastasis and poor patient prognosis." (PMID 26378045, 2015). "In addition, there is a positive correlation between the levels of H19 and NBAT1 lncRNAs in breast cancer blood samples, and the possible association among their functions remain to be confirmed in further studies." (PMID 36274054, 2023). "Furthermore, expression of NBAT1 was negatively associated with invasive potential of breast cancer cell lines." (PMID 26378045, 2015). "Assessments of lncRNAs profiles association with clinicopathological features of breast cancer patients showed that the expression level of NKILA, and NBAT1 lncRNAs were related to the tumor size." (PMID 36274054, 2023). "The effect of NBAT1 in breast cancer is mediated, at least in part, through DKK1, an inhibitor of Wnt (Wingless-related integration site) signaling pathway." (PMID 29443889, 2018). "lncRNA neuroblastoma associated transcript-1 (NBAT-1) is downregulated in numerous types of cancer, including breast cancer, which suggests a potential function as tumor suppressor." (PMID 27608009, 2016). "Taken together, these data indicated that down-regulation of NBAT1 expressions in breast cancer tissues was correlated with metastasis and poor patient prognosis." (PMID 26378045, 2015). "Specifically, we have demonstrated the correlation of NBAT1 expression with breast cancer metastasis, and therefore the potential value of harnessing it as a lncRNA prognostic marker." (PMID 26378045, 2015). "Among them, DKK1 (dickkopf WNT signaling pathway inhibitor 1) is found to be regulated by NBAT1 in a PRC2 dependent manner, and is responsible for NBAT1's effects in inhibiting migration and invasion of breast cancer cells." (PMID 26378045, 2015). "Taken together, our study demonstrates that long noncoding RNA NBAT1 is a potential breast cancer prognostic marker, as well as a potential therapeutic target to inhibit breast cancer metastasis." (PMID 26378045, 2015). "Compared with mammary epithelial cell lines, NBAT1 expression was down-regulated in the breast cancer cells." (PMID 26378045, 2015). "To further investigate the mechanisms of how NBAT1 represses migration and invasion of breast cancer cells, we explored global gene expression changes affected by forced expression of NBAT1 in MDA-MB-231 cells by microarrays." (PMID 26378045, 2015). "However, BC040587expression level was related to age, node metastasis, tumor size, and grade of breast cancer patients, and NBAT1 lncRNA expression was also correlated with the patients' age (p < .05)." (PMID 36274054, 2023). "DKK1 represents an inhibitor of the WNT signaling pathway and might be responsible for NBAT-1’s effect in suppressing migration and invasion of breast cancer cells." (PMID 27608009, 2016). "We further investigated whether NBAT1 mediates breast cancer cell migration and invasion using Boyden chamber assay with or without Matrigel coating, respectively, as well as the wound healing assay." (PMID 26378045, 2015). "In order to test whether NBAT1 regulates EZH2 functions, we then applied EZH2 inhibitors EI1 or GSK343 in MDA-MB-231 breast cancer cells with NBAT1 over-expression." (PMID 26378045, 2015).
breast carcinoma (continued). "To further investigate how NBAT1 up-regulated DKK1 via EZH2 in breast cancer, we applied chromatin immunoprecipitation (ChIP)-quantitative real-time PCR (ChIP-qPCR) to analyze trimethylation of histone H3 lysine 27 (H3K27me3) status at DKK1 gene, which is a marker of suppressed chromatin." (PMID 26378045, 2015). "Therefore, in the present study, we explored the functions and mechanisms of NBAT1 in breast cancer." (PMID 26378045, 2015). "The correlation of NBAT1 expression with invasiveness suggests NBAT1 might be involved in the regulation of invasiveness of breast cancer cells." (PMID 26378045, 2015). "In vitro, ectopic NBAT1 inhibits migration and invasion of breast cancer cells." (PMID 26378045, 2015). "Next we sought to determine whether NBAT1 regulates breast cancer cell invasion via EZH2." (PMID 26378045, 2015). "The results revealed that some circulating lncRNAs (MEG3, NBAT1, NKILA, GAS5, EPB41L4A‐AS2, Z38, and BC040587) were significantly down‐regulated in breast cancer patients compared to healthy women." (PMID 36274054, 2023). "To further investigate the roles of NBAT1 in breast cancer, we examined the expressions of NBAT1 in immortalized non-tumorigenic human mammary epithelial cell lines and breast cancer cell lines with different invasive potentials." (PMID 26378045, 2015). "In accordance to the previous findings, the expressions of NBAT1 in breast cancers were significantly lower than those in normal breast tissues (p < 0.001)." (PMID 26378045, 2015). "We found that NBAT1 could inhibit the migration and invasion of breast cancer, while the effect of NBAT1 over-expression on invasion was reversed by concomitant EZH2 inhibitors, suggesting that the effect of NBAT1 on cell migration and invasion might be mediated through EZH2." (PMID 26378045, 2015).
hepatocellular carcinoma (6 papers, 2020 to 2024). A malignant tumor that arises from hepatocytes. "It has also been reported that NBAT-1 affected gastric cancer, hepatocellular carcinoma and colorectal carcinoma in the digestive system." (PMID 38243168, 2024). "In hepatocellular carcinoma, NBAT-1 suppresses the stability of c-Myc mRNA by binding to IGF2BP1 and inhibiting their interaction, thereby inhibiting tumourigenesis through cell cycle blockade and increased apoptosis." (PMID 38243168, 2024). "It is known that NBAT1 plays an essential role in suppressing malignant cell proliferation and migration in multiple kinds of cancers, including renal carcinoma, hepatocellular carcinoma, and glioma." (PMID 35893039, 2022). "The lncRNA molecules NBAT-1 and FOXCUT have been found to have increased serum levels in patients with hepatitis C virus-induced hepatocellular carcinoma (HCC)." (PMID 37546394, 2023).
glioma (4 papers, 2022 to 2024). A benign or malignant brain and spinal cord tumor that arises from glial cells (astrocytes, oligodendrocytes, ependymal cells). "The formed NBAT1/miR-21/SOX7 axis represents the underlying molecular mechanism of NBAT1 functions in glioma." (PMID 37047365, 2023). "Additionally, Ning Guan and colleagues noticed that lncRNA Neuroblastoma Associated Transcript 1(NBAT1) was able to halt the evolution of glioma through the miR-21/SOX7 axis, demonstrating its therapeutic potential." (PMID 35619711, 2022). "NBAT1 is downregulated in glioma tissues compared with that in the paracarcinoma tissues and its expression was decreased in patients with metastatic glioma compared with the controls." (PMID 37047365, 2023). "In glioma, the results of a study by Ning Guan suggested that NBAT-1 may up-regulate SOX7 by inhibiting miR-21 to suppress the invasion, migration, and proliferation of glioma cells." (PMID 38243168, 2024). "In addition, NBAT1 expression was significantly decreased in aggressive (grade III or IV) compared with low-grade (I or II) glioma." (PMID 37047365, 2023).
lymph node metastasis (4 papers, 2015 to 2024). "There was altogether eight research focused on the relationship between lymph node metastasis and NBAT-1 expression, with statistically significant heterogeneity (P = 0.01, I2 = 60.10%)." (PMID 38243168, 2024). "Some lncRNAs, such as GAS5, rp11-190d6.2, and nbat-1 were downregulated in OV cells, and were significantly associated with histological grading, FIGO staging, and lymph node metastasis." (PMID 32950050, 2020). "Reduced NBAT1 was also significantly correlated with lymph node metastasis, as well as post-menopause status." (PMID 26378045, 2015). "Furthermore, RCCRT1, SPRY4-IT1, NBAT-1, MALAT1, and ATB might be used as biomarkers of lymph node metastasis." (PMID 27527868, 2016).
osteosarcoma (4 papers, 2018 to 2021). A usually aggressive malignant bone-forming mesenchymal neoplasm, predominantly affecting adolescents and young adults. "The low expression of LncRNA neuroblastoma associated transcript 1 (NBAT1) in osteosarcoma tissues and cells was closely correlated to clinical stages, lymph node metastasis and poor prognosis." (PMID 30217221, 2018). "NBAT1 overexpression downregulated osteosarcoma growth and metastasis via acting as a ceRNA against miR-21, which was associated with PTEN upregulation in vitro and in vivo." (PMID 30217221, 2018). "Neuroblastoma associated transcript 1 (NBAT1) is likewise downregulated in osteosarcoma tissues and five osteosarcoma cell lines (KHOS, LM7, 143b, USOS, and MG-63)." (PMID 29657304, 2018). "The expression of the lncRNA NBAT1 is downregulated in osteosarcoma tissues and cell lines." (PMID 31620370, 2019). "NBAT1 (NCBI GeneID: 729177) functions as a ceRNA against miR-21 to increase the expression of the miR-21 target gene PDCD4 and then suppresses osteosarcoma growth and metastasis in vitro and in vivo." (PMID 31620370, 2019).
gastric cancer (3 papers, 2018 to 2024). A primary or metastatic malignant neoplasm involving the stomach. "In contrast, neuroblastoma-associated transcript 1 (NBAT1), which interacts with Sox9 and reduces its protein stability, resulting in anti-angiogenesis, is downregulated in gastric cancer." (PMID 35052495, 2022). "Moreover, via the downregulated expression of PTEN, the growth of gastric cancer can be promoted by the low expression of NBAT-1, as revealed by Yuan Gao." (PMID 38243168, 2024).
ovarian carcinoma (3 papers, 2019 to 2024). A malignant neoplasm originating from the surface ovarian epithelium. "For example, lncRNA NBAT-1 is lowly expressed in ovarian cancer tissues, and inhibits proliferation, migration and invasion of ovarian cancer cells." (PMID 31123170, 2019). "Additionally, for other systems, NBAT-1 can affect the prognosis of other cancers.—In epithelial ovarian cancer (EOC), Changsheng Yan verified that NBAT-1 acts as an anti-oncogene and can be potentially used in EOC therapy by targeting the ERK1/2 and AKT signalling pathways." (PMID 38243168, 2024).
renal carcinoma (3 papers, 2021 to 2022). A carcinoma arising from the epithelium of the renal parenchyma or the renal pelvis. "Among all the lncRNA candidates predicted by the BiGAN as being associated with renal cancer, 7 lncRNAs were among the top 10 in the predicted list, (MALAT1 1st, HOTAIR 2nd, PVT1 3rd, NBAT1 4th, UCA1 5th, H19 6th, and MEG3 7th)." (PMID 34193046, 2021).
glioblastoma (2 papers, 2019 to 2020). The most malignant astrocytic tumor (WHO grade IV). "Up-regulation of a number of oncogenic lncRNAs such as H19, MALAT1, SNHGs, MIAT, UCA, HIF1A-AS2 and XIST in addition to down-regulation of other tumor suppressor lncRNAs namely GAS5, RNCR3 and NBAT1 indicate the role of these lncRNAs in the pathogenesis of glioblastoma." (PMID 33634032, 2020).